EGFR (epidermal growth factor receptor)
Diseases named in the same sentence as EGFR in open-access papers (continued):
Sharing a sentence is not in itself a finding about the gene and the disease.
tumor (continued). "Further, persistent downstream signaling through the RAS axis due to KRAS mutations can activate multiple processes involved in tumor progression and metastasis without the influence of EGFR and other cell surface receptor kinases." (PMID 31771279, 2019). "Realistically, radiosensitivity of the tested cell lines must be influenced not only by EGFR but also by other genetic aberrations; therefore, clinical tumor radioresponsiveness will be more accurately predicted by genetic profiles comprising multiple genes, which warrants further investigation." (PMID 31349558, 2019). "Almost all patients (7/8, 88%) had an overexpression of EGFR on their tumour tissues." (PMID 30634942, 2019). "Exosomal EGFR mediates metastasis and tumor immunity in lung cancer." (PMID 31620359, 2019). "Thus, the genetic backgrounds, such as mutant EGFR and RAS, need to be taken into consideration to better understand the association between tumor-initiating cells and therapeutic resistance in the future." (PMID 31816897, 2019). "Furthermore, EGFR-specific CAR-T cells exerted significant anti-tumor effects in both high-EGFR- expressing TNBC xenograft models." (PMID 31804974, 2019). "Furthermore, the internalized rLj-112 was also found to induce the internalization of EGFR and suppress the downstream signaling pathways to initiate the anti-tumor steps in B16 cells." (PMID 30821275, 2019). "Detecting tumor markers such as EGFR, ALK, ROS1, and PDL-1 in the blood or plasma might not only guide management, but also detect early therapy resistance, relapse, and establish a prognosis." (PMID 31818027, 2019). "Likewise, IgA2 anti-EGFR was proved to be more efficient than Cetuximab (IgG format) against tumour cells in a FcαRI transgenic mice model." (PMID 31817406, 2019). "We have therefore now evaluated AXL and GAS6 levels in both tumor tissue and plasma as well as their relation to clinical course in EGFR‐mutated NSCLC patients before treatment with and after the development of resistance to EGFR‐TKIs." (PMID 31419057, 2019). "To confirm that our CTC cell line originated from the primary lesion, we previous studies have demonstrated that the sequencing of CTC-TJH-01 cells exhibits wild-type EGFR and a missense mutation at codon 12 in exon 2 of KRAS, which is consistent with the mutation status found in the primary tumor." (PMID 30718976, 2019). "Another approach that could assess EGFR status within the entire tumor throughout the body could potentially provide more comprehensive information to predict whether a patient will respond to cetuximab treatment." (PMID 31651282, 2019). "Considering these results, we might guess that the retrovirus-transduced CD8 T cells to express EGFR could benefit from EGFR ligand concentrations found in the tumor microenvironment." (PMID 31921216, 2019). "According to our simulation results, EGFR overexpression is not able to significantly increase the growth rate of the tumour in the absence of other mutations." (PMID 31016574, 2019). "However, during the progression of HCC, Cx32 proteins internalize and chiefly regulate multiple signaling molecules and pathways, such as Bcl-2 protein family members and the EGFR signaling pathway, to promote tumor survival and prevent apoptosis." (PMID 30947731, 2019). "We first investigated if cytonemes are present in EGFR-Pcn overexpressing tumor cells." (PMID 31568500, 2019). "The first generation of EGFR-TKIs, such as gefitinib and erlotinib, blocks the further transmission of signals into cells by competitively binding to ATP-binding EGFR tyrosinase catalytic domain binding sites on the cell surface, thus inhibiting tumor cell growth and inducing apoptosis." (PMID 31832192, 2019).
tumor (continued). "In this study, we enrolled thirty‐six EGFR‐mutant advanced lung adenocarcinoma patients, who were confirmed T790M‐positive based on tumour tissue genotyping assay, and investigated the clinical implications of serial analysis using a 1021 gene capture panel of ctDNA during osimertinib treatment." (PMID 31393074, 2019). "This may be due to the significant reduction in tumor size obtained with first‐line EGFR‐TKI treatment." (PMID 31595714, 2019). "To evaluate a potential benefit that EGFR ligands produced by tumor cells might provide to modified T cells for tumor recognition, we examined the capacity of EGFR-transduced OT-1 CD8+ T cells to recognize and lyse tumor cells expressing ovalbumin." (PMID 31921216, 2019). "The concept that EGFR alterations could drive tumour growth established the hypothesis that tyrosine kinase inhibitors could have antitumor effects." (PMID 31739412, 2019). "Alternate treatment options for NF2 tumours include inhibitors of the epidermal growth factor receptor (EGFR), inhibitors of the vascular endothelial growth factor (VEG-F), inhibitors of mTORC1, an inhibitor of platelet-derived growth factor (PDGF), and an inhibitor of histone deacetylase (HDAC)." (PMID 31730023, 2019). "This novel form of dual CAR targeting was demonstrated by Choi and colleagues to be effective in the clearance of heterogeneous EGFRvIII/EGFR expressing tumours in vivo, where a tumour-specific EGFRvIII CAR simultaneously secreted an EGFR-specific BiTE into the tumour microenvironment." (PMID 31892219, 2019). "However, EGFR-targeted therapies have shown suboptimal performance in clinical trials for EGFR overexpressing HNSCC tumours." (PMID 31827134, 2019). "Moreover, inhibiting miR-21 expression promotes apoptosis in these cells and suppresses tumor growth in nude mice treated with EGFR-TKIs." (PMID 31266248, 2019). "This anti-tumor activity of NK cells could be significantly enhanced by cetuximab or avelumab, particularly in cells with higher baseline EGFR or PD-L1 expression." (PMID 31510065, 2019). "Altogether, these results suggest that IL-1α in combination with cetuximab can induce a T cell-dependent anti-tumor immune response and may represent a novel immunotherapeutic strategy for EGFR-positive HNSCCs." (PMID 30890189, 2019). "The expression levels of EGFR in the immunohistochemistry analysis were significantly correlated with a positive pN status (P = 0.030), overall pathological stage (P = 0.041), perineural invasion (P = 0.038), and tumor depth (P = 0.037)." (PMID 30914776, 2019). "Importantly, we also observed a downregulation of EGFR and an induction of cellular senescence in tumor xenografts in mice treated with Nutlin-3a." (PMID 30910997, 2019). "Furthermore, preclinical results have shown that EGFR activation can upregulate intrinsic PD-L1 expression on tumor cells, which induces T cell apoptosis and contributes to the immune escape of EGFR-mutant NSCLC." (PMID 31526368, 2019). "EGFR amplification was detected in 2 tumours with the intestinal subtype." (PMID 30837681, 2019). "Comprehensively, the alteration of EGFR in LGG might changes the TME and triggers a tumor-associated chronic inflammation, which eventually affect the functions of tumor infiltrated immune cells." (PMID 31801484, 2019). "We also found a significant interaction (p=0.02) between the 2/1 IL-1α profile score and EGFR+ expression suggesting that this particular 2/1/EGFR+ expression profile could be considered a predictor of tumor recurrence." (PMID 31320902, 2019). "Activin A and EGFR were highly expressed in the cytoplasm and membrane of the tumor cells." (PMID 30914776, 2019).
tumor (continued). "In a high proportion (~30%) of non-small cell lung cancer (NSCLC) patients, the oncogenic driver of tumor growth is the constitutively activated epidermal growth factor receptor (EGFR, HER-1/ErbB1), a receptor tyrosine kinase of the ErbB family, which has been identified as an anticancer target." (PMID 31323891, 2019). "TKI based regimens consistently showed the greatest benefit over docetaxel (75 mg/m2) in patients with EGFR mutation positive tumor types regardless of histology." (PMID 30987609, 2019). "Compared to control group, the expression of EGFR protein of challenged group was down-regulated, which suggested that T. gondii infection might inhibit the growth of NON-SMALL CELL LUNG tumor by reducing the expression of EGFR protein." (PMID 30792708, 2019). "In addition, immunohistochemical analysis performed in pretreatment tumor biopsies revealed a beneficial role of high EGFR expression in patients assigned to CHART, compared with those receiving conventionally fractionated RT." (PMID 30652016, 2019). "However, the decrease in tumor accumulation after 3 h after injection would limit sensitivity for discerning subtle changes in EGFR expression." (PMID 30213849, 2019). "However, if only patients with 2/1/EGFR+ tumors are taken into account, 94% of these patients experienced tumor recurrence with a median survival of 7 months." (PMID 31320902, 2019). "Existing evidence indicates that resistance to EGFR-TKIs could be acquired through epigenetic and genetic changes in cancer cells, as well as tumor microenvironment activation." (PMID 31750252, 2019). "For patients with EGFR mutation-positive, ALK rearrangement-positive or ROS1 rearrangement positive tumours first-line molecular targeted tyrosine kinase inhibitors are recommended, while patients with high PD-L1 expression in the tumour are suitable for pembrolizumab first-line treatment." (PMID 31088547, 2019). "PCSK5 expression is a predictor for tumor response to the EGFR tyrosine kinase inhibitor erlotinib." (PMID 31101650, 2019). "Unlike the nonselective Erbitux-based CAR, EGFR806-CAR T cells did not target primary human fetal brain astrocytes expressing wild-type EGFR, but showed a similar level of activity compared to Erbitux-CAR when the tumor-specific EGFRvIII transcript variant was overexpressed in astrocytes." (PMID 31903167, 2019). "Secondly, data on EGFR mutational status was only available for 42 (77.8%) patients and no data was available on other tumor mutations (e.g. ALK, ROS1, BRAF) for which targeted treatments now exist." (PMID 30973926, 2019). "Mutations in EGFR were detected in 8/17 (47%) patients at disease progression, which were not present at baseline, neither in ctDNA nor in tumor tissue." (PMID 31350822, 2019). "Moreover, one ARMS-classified EGFR(-) tumor was reported as EGFR(+) by NGS in all liquid biopsy samples, suggesting a true call by NGS method." (PMID 31534501, 2019). "Additionally, EGFR targeting enhances IR-induced apoptosis, inhibits proliferative growth, and downregulates tumor angiogenic response." (PMID 30621219, 2019). "Moreover, EGFR-FITC-SiO2-NPs were detected in the tumor and the liver in the CAM assay while FITC-SiO2-NPs were only rarely detected in the liver." (PMID 31561451, 2019). "The potency of systemic delivery of Erb-sumIL2 targeting to the EGFR positive tumor was tested." (PMID 31462678, 2019). "Moreover, the IL-1α gene has been reported to be regulated by sp1 suggesting a feed-forward relationship between IL-1α and sp1 which would ultimately promote EGFR signaling and tumor progression." (PMID 31320902, 2019).
tumor (continued). "Meanwhile, the results of western blot and immunohistochemistry (IHC) assay also demonstrated the EhCv/siEGFR NPs could exhibit the best downregulation of EGFR protein in tumor tissues." (PMID 31221991, 2019). "p16 status (p < 0.001), smoking above 10 pack years (p = 0.04), smoking above 20 pack years (p < 0.001), total EGFR tumor levels (p = 0.016), and high EGFR within high or low Ki67 tumor nuclear staining (p = 0.03) were found to be significant predictors of 5-year disease specific survival (DSS)." (PMID 30630536, 2019). "This is likely due to the lower EGFR expression levels detected on wildtype cells, although others have shown that tumor cells also produce more ROS than wildtype cells, which might also influence PDT responses." (PMID 31694307, 2019). "However, studies based on tumor models have shown that CTGF can act as a ligand of EGFR, stimulate EGFR activation, and play a role in promoting tumor cell proliferation and even tumor cell EMT." (PMID 31200637, 2019). "EGFR expression is also correlated with lower histologic tumor differentiation." (PMID 31159251, 2019). "Nevertheless, our study is one of the few real-life studies that have specifically addressed the prognostic and predictive role of tumor sidedness in RAS wt mCRC patients treated in first-line with a combination of chemotherapy plus anti-EGFR agents or Bevacizumab." (PMID 31762802, 2019). "Analysis of pre-treatment tumor tissue revealed higher genetic heterogeneity in patients who developed resistance, emphasising the idea of clonal evolution and selective pressure from anti-EGFR therapy." (PMID 31824558, 2019). "The presence of circulating free tumour DNA for the mutations BRAF, K-ras, N-ras, and PIK3CA mutations has been used to identify patients with MRD and also as a marker for the resistance to EGFR therapy, such as cetuximab or panitumumab." (PMID 31281432, 2019). "The fitting of fractional polynomial models for OS was problematic because these models were not able to differentiate between the efficacy of TKIs for EGFR mutation-negative and mutation-positive tumor types." (PMID 30987609, 2019). "Inflammatory features like PD-L1 expression may be affected by traditional stratifying criteria (i.e. gender, age, smoking status, histology, tumor stage or KRAS/EGFR status)." (PMID 31125352, 2019). "The tumor was EGFR+ in a group of 24 patients and KRAS+ in another set of 24 subjects." (PMID 30999636, 2019). "Finally, the anticancer potency of kaempferol was further confirmed in a mice xenograft model, revealing the ability to significantly prevent the growth of tumor size coupled with a marked decrease in hexokinase-2 expression and EGFR activity in tumor tissues." (PMID 31248102, 2019). "This concept is well expressed in the ESMO (European School of Medical Oncology) guidelines in relation to the diversity of the initial treatment intent, suggesting the use of CT doublets and anti-EGFR (panitumumab or cetuximab) when the main objective is a rapid tumor shrinkage." (PMID 31500586, 2019). "Importantly, EGFR-expressing OT-1 T cells injected into B16-OVA tumor bearing mice were recruited into the tumor, expressed lower levels of the exhaustion markers PD1, TIGIT, and LAG3, and were more efficient in delaying tumor growth." (PMID 31921216, 2019). "In these animals, expression of EGFR, Pcn, and NrgRNAi is driven by ap-Gal4 continuously after the second instar, but the noxious effects of NrgRNAi suppress the tumor phenotype induced by EGFR and Pcn overexpression and are tolerated by the disc cells in which NrgRNAi is expressed." (PMID 31568500, 2019). "In this study, we established GSC neurospheres from patient tumour samples harvested before and after treatment with an EGFR-targeted agent, and analysed the molecular and biological characteristics that the GSC and patient tumour specimens exhibited pre- and post-treatment with this targeted drug." (PMID 30644426, 2019).
tumor (continued). "However, despite gefitinib reaching high concentrations in GBM tumour tissue (22-fold higher compared to plasma) and the significant dephosphorylation of EGFR achieved, limited clinical effects have been observed in Phase II trials." (PMID 31616641, 2019). "Therefore, it is likely that EGFR antagonist can interfere in the function of these leukocytes, contributing to the clinical efficacy of anti-tumor treatments." (PMID 31370270, 2019). "However, results from meta-analyses suggest the superiority of anti-EGFR agents over Bevacizumab in this tumor subtype 14-16." (PMID 31762802, 2019). "EGFRvIII, which lacks the extracellular ligand-binding domain, could constitutively activate the EGFR signaling pathway, leading to the malignant progression of tumor cells and modulation of the tumor microenvironment." (PMID 31532757, 2019). "Furthermore, some drugs, such as vandetanib, have been designed to inhibit tumor growth by targeting EGFR and VEGFR at the same time, which have been under clinical trials." (PMID 31074391, 2019). "In various cancers, FDG PET may also allow monitoring of tumor response to therapies targeting the EGFR pathway." (PMID 31532771, 2019). "We synthesized silica nanoparticles with an average size of 45 nm and modified these particles with the fluorescence stain fluorescein isocyanate (FITC) for particle detection and with epidermal growth factor receptor (EGFR)-targeting antibodies for enhanced tumor specificity." (PMID 31561451, 2019). "The majority of the patients analyzed with tumor tissues were to find targeted agents for the first time, while some of the patients analyzed with blood samples showed the presence of resistance developed towards EGFR-TKIs." (PMID 31749831, 2019). "Similarly, in the EXTREME trial of first-line use of platin/5-fluorouracil/cetuximab in relapsed or metastatic disease, outcomes were essentially identical for patients with less than or more than 40% EGFR-positive tumor cells." (PMID 30213849, 2019). "Furthermore, IF for p-EGFR expression was performed on these tumor masses, and in accordance with the IHC results, a recovery in p-EGFR activation was observed upon the co-administration of Gefitinib with OA." (PMID 30876460, 2019). "Overall, EGFR signal was relatively weak in our sample set and few of the samples had high cytoplasmic and membranous staining (3/21; 14%); however, in an additional number of tumors scattered, high expressing tumor cells were observed." (PMID 31506424, 2019). "Tumours with somatic mutations such as BRAF, EGFR or gene rearrangements such as ALK are considered therapeutic options regardless of tumour type or location, and tumours may even be characterised as BRAFomas or ALKomas." (PMID 30667539, 2019). "Therefore, distinctive micro-environmental influences on NSCLC in vitro tumor model with co-cultured CAFs and patient derived tumor cells (EGFR T790M mutants) will be helpful for better understanding of stromal contribution to NSCLC." (PMID 31882581, 2019). "We designed a CAR using a mAb806-based binder, which recognizes tumor-specific untethered EGFR." (PMID 31903167, 2019). "For instance, NCK1 is required for EGFR-mediated cell migration and tumor metastasis." (PMID 31214250, 2019). "Even if the tumor develops resistance to conventional EGFR-TKIs, it is important to recognize that drugs such as osimertinib are available and may improve long-term survival." (PMID 30681568, 2019). "Although primary tumor sample is standard starting material to perform genetic analyses, limiting factor is the obtained DNA cannot indicate genetic and epigenetic changes, such as acquired resistance to EGFR inhibitor, which is a major issue worldwide." (PMID 30954079, 2019).